HOXA10 (homeobox A10)
Diseases named in the same sentence as HOXA10 in open-access papers (continued):
Sharing a sentence is not in itself a finding about the gene and the disease.
adenomyosis (continued). "Integrated optical density (IOD) measurements of the HOXA10 (P < 0.01) and IL-10 (P < 0.05) proteins were significantly lower in women with adenomyosis than in normal controls." (PMID 30687738, 2018). "To assess the mechanisms by which adenomyosis affects implantation, we detected the expression of the endometrial receptivity marker protein HOXA10 and the anti-inflammation cytokine IL-10 in women with adenomyosis." (PMID 30687738, 2018). "A significant decrease in the expression of HOXA-10 gene during the midluteal phase has been documented in women with adenomyosis." (PMID 29234680, 2017). "Reduced HOXA10 expression is also seen in animal models of Tamoxifen-induced adenomyosis, which may be brought on by overexpression of HIF-2α, dysregulation of IL-10, or IL-33/p-STAT3 signaling." (PMID 40305321, 2025). "Further studies are needed to determine whether these epigenetic changes are also accountable for progesterone resistance and reduced HoxA10 expression in adenomyosis." (PMID 38451875, 2024). "Moreover, the regression analysis revealed the presence of adenomyosis to be the only predictor of HOXA10 expression, significantly affecting expression levels within the stroma." (PMID 39274229, 2024). "The drop of HOXA10 gene expression was also observed in women with adenomyosis and a decreased rate of proper implantation The presence of this transcription factor was also confirmed in pigs, in both, the endometrium and conceptuses, and its expression raised during the peri-implantation period." (PMID 38773369, 2024). "In addition, HOXA-10 was found to be down-regulated in women with adenomyosis, as well as in experimental adenomyosis in mouse models." (PMID 37569402, 2023). "In our study, we found endometrial IL33 expression was positively correlated to HOXA10 expression and may involve embryo implantation in patients with adenomyosis." (PMID 35937844, 2022). "In the present study, we showed that intracellular protein level of IL-33 was downregulated in the endometrium of patients with adenomyosis, and IL-33 expression status was shown to be positively correlated with that of HOXA10, an endometrial receptivity marker." (PMID 35937844, 2022). "Therefore, the exact functions of IL-10 and HOXA10 during decidualization in women with adenomyosis should be further assessed." (PMID 30687738, 2018). "The abnormal expression of IL-10 and HOXA10 in the stroma might impair the decidualization of endometrial stromal cells in adenomyosis patients, which would result in implantation failure." (PMID 30687738, 2018). "We speculate that dysregulation of the IL-10/p-STAT3/HOXA10 signaling pathway results in embryo implantation failure in women with adenomyosis." (PMID 30687738, 2018). "In this study, we demonstrated reduced IL-10, p-STAT3, and HOXA10 expression in the endometrium of adenomyosis patients, which might lead to impaired embryo implantation." (PMID 30687738, 2018). "In addition, the mean expression of IL33 in normal controls (0.1783 ± 0.025) was higher than that in adenomyosis (0.1415 ± 0.0071), p=0.00182; the mean densities of HOXA10 in the fertile and adenomyosis individuals were 0.3003 ± 0.055 and 0.1878 ± 0.036, p=0.0050." (PMID 35937844, 2022). "However, the molecular mechanism of HOXA10 downregulation in adenomyosis patients is unclear." (PMID 35937844, 2022). "Eutopic endometrium from adenomyosis patients is characterized by an abnormal expression of a number of receptivity markers, namely PR, LIF, HOXA10 and osteopontin." (PMID 39274229, 2024). "We found that in the endometria of patients with adenomyosis, both IL33 and HOXA10 expression were lower." (PMID 35937844, 2022). "The endometrial receptivity marker HOXA10 and its downstream target molecule ITGB3 were both decreased in the adenomyosis mouse model as well as during the secretory phase in patients with adenomyosis." (PMID 35937844, 2022).
adenomyosis (continued). "The expression level of the endometrial receptivity marker HOXA10 was significantly increased after combined administration of GnRHa and CCL21 in the uterus of mice with adenomyosis." (PMID 35022045, 2022). "As IL-10 induced HOXA10 expression through phosphorylation of STAT3, we further detected p-STAT3 and STAT3 protein expression in the endometria of women with adenomyosis and normal controls." (PMID 30687738, 2018). "The expression levels of IL-10, HOXA-10, STAT3, and p-STAT3 in the endometrium of women with adenomyosis and controls were examined by means of western blotting and immunohistochemistry." (PMID 30687738, 2018). "Abnormal expression levels of several implantation-related factors (such as HOXA10, LIF, MMP2, interleukin-6, cytochrome P450, and RCAS1) in the eutopic endometrium of women with adenomyosis have been found to result in impaired embryo implantation." (PMID 30687738, 2018). "Thus, the downregulation of HOXA10 and HOXA11 expression by HIF-2α overexpression may be involved in the pathogenesis of adenomyosis in mice." (PMID 36834456, 2023). "Additionally, studies with experimental animal models for adenomyosis revealed that the expression of hypoxia-inducible factor-2α (HIF-2α) in the adenomyosis group was higher than in the control group and that HIF-2α antagonists increased the mRNA and protein expression of HOXA10 and HOXA11." (PMID 36834456, 2023).
acute myeloid leukemia (18 papers, 2010 to 2025). Acute myeloid leukemia (AML) is a group of neoplasms arising from precursor cells committed to the myeloid cell-line differentiation. "Humans possess 39 HOX genes across seven families, with specific genes like HOXB3, HOXB4, and HOXA1 to HOXA10 linked to adverse outcomes in diseases such as acute myeloid leukemia (AML)." (PMID 39200378, 2024). "High expressions of HOXA7, HOXA9, and HOXA10 are frequently seen in acute myeloid leukaemia (AML) and the overexpression of HOXA9 is linked to a poor prognosis." (PMID 28515451, 2017). "For instance, loss of HOXA5 in breast cancer, over-expression of HOXA10 in acute myeloid leukemia (AML), gene mutations of HOXD4 in renal and colon cancer and overexpression of HOXC4 in human bladder cancer have been reported." (PMID 22768238, 2012). "Increased expression of a set of homeodomain transcription factors, including HoxA10, characterizes an adverse prognosis subtype of acute myeloid leukemia (AML)." (PMID 40680841, 2025). "HOXA10 is another oncogene that is overexpressed in acute myeloid leukemia, NPC, and many other cancers." (PMID 33564686, 2021). "UBE2E1 links with HOX gene regulation for its prognostic role in acute myeloid leukemia because HOX gene (HOXA9 and HOXA10) promotes acute myeloid leukemia leukemogenesis." (PMID 34769401, 2021). "Previous studies show that Mll modulates myeloid cell differentiation by regulating HOXA10 gene expression in acute myeloid leukemia cells." (PMID 29363553, 2018). "Overexpression of HOXA10 in hematopoietic cells blocks myeloid/lymphoid differentiation and drives acute myeloid leukemia, indicating a critical role of HOXA10 in differentiation inhibition and tumorigenesis." (PMID 30545354, 2018). "HOXA10, a homeobox-containing gene involved in definitive haematopoiesis, which implicated in the pathogenesis of AML (acute myeloid leukaemia), has been studied extensively." (PMID 25307539, 2014). "In particular, the HOXA9 and HOXA10 homeobox genes are frequently over-expressed in acute myeloid leukemias (AMLs)." (PMID 20846384, 2010). "Additionally, in acute myeloid leukemia (AML), WBP5 overexpression has been associated with poor prognosis, correlating with increased expression of HOX gene cluster (HOXA5, HOXA7, HOXA9, and HOXA10), MEIS1, and FOXC1." (PMID 40002180, 2025). "A poor prognosis subtype of acute myeloid leukemia (AML) is characterized by increased expression of a set of homeodomain (HD) transcription factors, including HoxA9, HoxA10 and Cdx4." (PMID 27340869, 2016). "Mice transplanted with HoxA10 overexpressing bone marrow develop granulocytosis that evolves to acute myeloid leukemia (AML) over time." (PMID 27340869, 2016). "Concomitantly elevated expression levels of HOXA9 and HOXA10 together with ID2 in cell lines containing MLL translocations confirmed this form of regulation in both ALL and acute myeloid leukemia." (PMID 20565746, 2010). "However, overexpression of HOXA10 in murine bone marrow has been shown to induce a myeloproliferative disorder (MPD) involving expansion of the committed myeloid progenitors, which later evolves into acute myeloid leukemia (AML)." (PMID 29593731, 2018). "Acute myeloid leukemia (AML) with mixed lineage leukemia 1 (MLL1) gene rearrangement is characterized by increased expression of a set of homeodomain transcription factors, including homeobox A9 (HOXA9) and HOXA10." (PMID 32467231, 2020).
endometrial cancer (14 papers, 2008 to 2025). Primary or metastatic malignant neoplasm involving the endometrium (mucous membrane that lines the endometrial cavity). "The loss of HOXA10 expression has been reported to cause endometrial hyperplasia leading to endometrial cancer." (PMID 36979165, 2023). "For example, the expression of miR-139-5p is observably reduced in endometrial carcinoma, and miR-139-5p can target HOXA10 to restrain cancer cell multiplication and migration." (PMID 33517826, 2021). "H19 regulates the expression of its target gene HOXA10 in endometrial carcinoma by competing with miR-612." (PMID 34130625, 2021). "The tumor suppressor function of miR-139-5p involves targeting HOXA10 to inhibit endometrial cancer cell growth and migration." (PMID 32754277, 2020). "The expression of HOXA10 was detected by Immunofluorescence staining in endometrial cancer tissues and adjacent normal tissues." (PMID 29618950, 2018). "The expression level of HOXA10 was significantly increased in endometrial cancer tissues, which was inversely correlated with miR-139-5p expression in clinical endometrial cancer tissues." (PMID 29618950, 2018). "Downregulation of HOXA10 expression in endometrial carcinomas correlates with increased tumor grade and promotes tumor growth and invasive properties." (PMID 25136598, 2014). "HOXA10 inhibits expression of Snail, a zinc-finger transcription factor, in endometrial carcinoma cells." (PMID 25136598, 2014). "Forced expression of HOXA10 in endometrial carcinoma (SPEC2 and KLE) cells induces E-cadherin expression, suppresses vimentin expression, and inhibits their invasive behavior." (PMID 25136598, 2014). "Furthermore, human endometrial cancer cell lines that overexpressed HOXA10 showed decreased cell proliferation, indicating that HOXA10 regulates the growth of epithelial cells." (PMID 40305321, 2025). "It targets the HOXA10 transcript and suppresses endometrial carcinoma cell growth and migration." (PMID 37958433, 2023). "For example, miR-139 can suppress endometrial cancer cell growth and migration via down-regulation of HOXA10, restore docetaxel-chemosensitivity by targeting Notch1, decrease tumor cell over-proliferation and EMT process in metastatic prostate and colorectal cancer cells." (PMID 34070538, 2021). "This study indicates the levels of miR-139-5p in EC tissues were markedly reduced compared to normal endometrium tissues and overexpression of miR-139-5p in endometrial cancer cells markedly reduced cell viability and migration, and suppressed HOXA10 expression." (PMID 29618950, 2018). "Previously, we showed that HOXA10 regulates G1 phase arrest in endometrial cancer which may be mediated by p21." (PMID 29618950, 2018). "HOXA10 expression was downregulated in endometrial cancer cells after miR-139-5p overexpression." (PMID 29618950, 2018). "In addition, PBX2 and HOXA10 interactions with EMX2 were demonstrated in endometrial cancer cell lines." (PMID 18973687, 2008). "In addition, downregulation of HOXA10 expression in endometrial carcinoma cells is responsible for their invasive behavior, which might be due to the effect of HOXA10 on the inhibition of EMT by inducing the expression of epithelial cell adhesion molecule E-cadherin." (PMID 31013831, 2019).
lung adenocarcinoma (13 papers, 2017 to 2026). A carcinoma that arises from the lung and is characterized by the presence of malignant glandular epithelial cells. "RESULTS: Our study demonstrated that HOXA10 is upregulated in our lung adenocarcinoma mouse model and in early-stage clinical lung adenocarcinoma specimens." (PMID 41736051, 2026). "CONCLUSION: During early lung adenocarcinoma development, tumor cells acquire immune evasion capabilities through HOXA10 upregulation, which remodels the intra-tumoral immune microenvironment and promotes adenocarcinoma initiation and progression." (PMID 41736051, 2026). "Circular RNA circCSNK1G3 can induce HOXA10 expression via the sponge of has-miR-143-3p, improving the growth and metastasis of lung adenocarcinoma cells." (PMID 38531930, 2024). "In the following experiments, miR‐195 was observed to be down‐regulated but HOXA10 was up‐regulated in lung adenocarcinoma." (PMID 31967713, 2020). "The upregulation of miR-144 enhances LINC00483 and Homeobox A10 (HOXA10) genes in lung adenocarcinoma, resulting in a tumor suppressor activity through the regulation of EMT." (PMID 32276343, 2020). "TCGA database demonstrated a high expression of LINC00461 and HOXA10 in lung adenocarcinoma, while miR‐195 had poor expression in lung adenocarcinoma." (PMID 31967713, 2020). "Our study showed that LINC00461 functioned as a competing endogenous RNA to regulate HOXA10 expression by binding to miR‐195 in lung adenocarcinoma cells." (PMID 31967713, 2020). "Our study aims to investigate the underlying molecular mechanisms of LINC00461/microRNA‐195 (miR‐195)/HOXA10 responsible for its involvement in lung adenocarcinoma." (PMID 31967713, 2020). "Similarly targeting of HOXA10 by miR-195-5p and an inverse relationship between them is reported in lung adenocarcinoma." (PMID 39095857, 2024). "In addition, LINC00355 and LINC00461 act as a miR-195 sponge to promote cell proliferation, invasion, and migration to up-regulate HOXA10 in head, neck squamous cell carcinoma, and lung adenocarcinoma, respectively." (PMID 35574307, 2022). "Furthermore, the silencing of LINC00461 can evidently enhance the radiosensitivity of lung adenocarcinoma cells via miR-195-mediated HOXA10 downregulation." (PMID 33869744, 2021). "Therefore, this study was planned to explore the regulatory mechanism of the LINC00461/miR‐195/HOXA10 regulatory network in lung adenocarcinoma." (PMID 31967713, 2020). "Subsequently, the key findings obtained from this study provided evidence that LINC00461 silencing could potentially suppress lung adenocarcinoma cell migration, invasion while enhancing radiosensitivity via downregulation of HOXA10 by binding to miR‐195." (PMID 31967713, 2020). "In addition, lung adenocarcinoma cells showed decreased HOXA10 and increased miR‐195 following LINC00461 silencing." (PMID 31967713, 2020). "Forced LINC00461 expression decreased expression of miR‐195 and Bax, increased expression of HOXA10, MMP‐2, MMP‐9 and Bcl‐2, promoted cell proliferation, migration and invasion as well as tumour formation, and enhanced radiosensitivity of lung adenocarcinoma cells." (PMID 31967713, 2020). "HOXA10, HOXA11, and HOXA13 might be useful targets to further mine the molecular pathogenesis of HOXA11 in early-stage lung adenocarcinoma." (PMID 29914539, 2018).
prostate carcinoma (12 papers, 2017 to 2024). A carcinoma that arises from epithelial cells of the prostate gland. "In another study on prostate cancer, HOXA2, HOXA9, and HOXA10 were identified as critical genes, which were both abnormally expressed and associated with clinical outcomes of patients with prostate cancer." (PMID 36159969, 2022). "HOXA13, HOXA1, HOXA5, HOXA6, HOXA7, HOXA9, and HOXA10 are involved in prostate cancer, and they form a DNA loop with a locus that induces prostate cancer and regulates gene transcription." (PMID 37590265, 2023). "The disruption or abnormal expression of HOXA10 thereby promotes the malignant behavior of tumor cells, especially in prostate cancer, in which a tumor-suppressor role of HOXA10 was identified." (PMID 35625802, 2022). "HOXA10 exerts an oncogenic role in several tumors, including ovarian clear cell adenocarcinoma, oral squamous cell carcinoma, prostate carcinoma and endometrial adenocarcinoma." (PMID 30545354, 2018). "As for tumorigenesis, HOXA10 participates in ovarian clear cell adenocarcinoma, oral squamous cell carcinoma, prostate carcinoma, gastric cancer, endometrial adenocarcinoma and so on." (PMID 30545354, 2018). "In testicular and prostate cancers, HOXA10 plays a tumor suppressive role." (PMID 32841292, 2020). "It has been reported that during the progression of prostate cancer (PCa), aberrantly expressed HOXA2, HOXA9, and HOXA10 facilitate the infiltration of dendritic cells, macrophages, and mastocytes." (PMID 38904676, 2024). "Hypoxia-inducible miR-1181 is a known tumour suppressor in cancers such as pancreatic, ovarian and prostate cancer and is shown to target SOX2, STAT3 and HOXA10 to inhibit proliferation, migration and invasion and to promote EMT43–47." (PMID 35190587, 2022). "The miR-135a reduces the invasion and metastasis of prostate cancer by inhibiting ROCK123 and induces the apoptosis of various cells by inhibiting HOXA10 and BCL-2 expression." (PMID 28729631, 2017). "Both HOXA10 and HOXD13 can promote the occurrence and development of various cancers by increasing the expression of genes and activating signal pathways, nevertheless, both of them can inhibit the expression of genes and suppress the occurrence of prostate cancer." (PMID 36685890, 2022).
colorectal cancer (11 papers, 2016 to 2024). A primary or metastatic malignant neoplasm that affects the colon or rectum. "HOXA10, a transcription factor, has been previously associated with the promotion of colorectal cancer development." (PMID 39334363, 2024). "In contrast, miR-27b-3p accelerated tumor progression via PPARG and HOXA10 in triple-negative breast cancer and colorectal cancer, respectively." (PMID 36306007, 2022). "For example, in colorectal cancer, overexpression of HOXA10 results in low survival rate and forecasts poor prognosis." (PMID 34294084, 2021). "miR-27b-3p promoted migration and invasion in colorectal cancer cells by targeting HOXA10/integrin β1 cell signal axis." (PMID 32676506, 2020). "Upregulation of HOXA10 expression plays a key role in colorectal cancer development and could be considered as a new biomarker that indicates poor prognosis." (PMID 34606634, 2021). "In colorectal cancer, LINC01089 can upregulate HOXA10 expression by sequestering miR-27b-3p, thereby inhibiting the proliferation and invasion of colorectal cancer cells." (PMID 39334363, 2024). "We saw upregulation of hsa-miR-196a-5p and hsa-miR-196b-5p in colorectal carcinoma tissue as compared to normal colorectal mucosa; we subsequently saw a direct relationship with hsa-miR-196a-5p and HOXB7 and hsa-miR-196b-5p with HOXA10 in colonic carcinoma tissue." (PMID 27123865, 2016).